INS (insulin)
Diseases named in the same sentence as INS in open-access papers (continued):
Sharing a sentence is not in itself a finding about the gene and the disease.
cancer (continued). "Additionally, GLUT4 expression and insulin-stimulated glucose uptake were also described in some cancer cell lines." (PMID 31936350, 2020). "Among these pathways of 4 wpe, pathways in cancer, viral carcinogenesis, glutamatergic synapse, cholinergic synapse, axon guidance, insulin signaling, lysosome, Toll-like receptor signaling pathway and Fc gamma R-mediated phagocytosis were targeted by more than 5 DEmiRNAs." (PMID 33332355, 2020). "Additionally, a further connection between insulin-resistant conditions and cancer is the link between hypoxia and new vascularization in tridimensionally growing tumor formations, which constitutes a key requirement for tumors’ malignant transition." (PMID 33266015, 2020). "Further investigations are required to identify the complex biological role and detail molecular mechanisms of each IGFBP in different cancer types and their relationship with insulin and plasma glucose to elucidate the relationship between cancers and type II DM." (PMID 32500027, 2020). "Current studies have identified the roles of CPA4 in cancer biology and insulin sensitivity." (PMID 32347291, 2020). "Indeed, metformin can interfere with cancer metabolism by interacting not only with the pathways of adenosine monophosphate kinase and the mammalian target of rapamycin, but also with insulin itself and IGF-1." (PMID 32708201, 2020). "Furthermore, arachidonic acid metabolism, PPAR signaling pathway, insulin resistance, eicosanoids signaling, and other pathways have also been reported in cancer." (PMID 33050938, 2020). "We observed the PI3K-Akt signaling pathway, ErbB signaling pathway, mTOR signaling pathway, MAPK signaling pathway, transcriptional misregulation in cancer, pathways in cancer, and insulin signaling pathway were most commonly affected in the milk-siblings group in comparison to controls." (PMID 33133155, 2020). "In vitro, insulin is a growth stimulator that is more potent than IGF-1 in some cancer cells." (PMID 32156062, 2020). "A surprising finding in recent articles is that METF might be useful in the prevention and treatment of several common cancers: it acts through both insulin-dependent and insulin-independent mechanisms." (PMID 30774659, 2019). "Epidemiologically too, lifestyle patterns resulting in high blood glucose level, with or without the role of insulin, are more often correlated with cancer risk, progression, and mortality." (PMID 31546918, 2019). "Hyperinsulinemia contributes to the development of cancer due to the direct effects exerted by insulin promoting growth, and indirectly, due to the decrease of circulating levels of IGF-1 binding proteins (IGFBP3), which increases the bioavailability of this growth factor." (PMID 31380268, 2019). "In the L-OA group, genes from the dark olive green module were significantly enriched for fatty acid degradation processes, while miRNA target genes from turquoise, pink, and blue modules were enriched for AMPK, insulin signaling pathway, and proteoglycans in cancer, respectively." (PMID 31354792, 2019). "The mechanism about physical activity reducing the mortality in cancer survivors was unknown, but some researches showed that it could improve survival by regulating the immune function, inflammation, modulating the insulin pathway, and epigenetic changes." (PMID 31772591, 2019). "Previously it has been delineated from our laboratory that dermcidin could induce anomalous platelet aggregation in AIHD and also impaired nitric oxide and insulin activity and furthermore dermcidin was also found in a few types of cancer patients." (PMID 31300527, 2019). "Pathways including glutathione metabolism, wnt signaling, central carbon metabolism in cancer, mTOR signaling, pancreatic secretion, protein and fat digestion, insulin secretion, and salivary secretion might be closely related with CCA development." (PMID 31687280, 2019).
cancer (continued). "In contrast, insulin and oral insulin secretagogues, including sulfonylureas and glinide, markedly increased HCC risk by 1.3–2.6 fold, likely by elevating serum insulin concentrations, which promote cancer cell proliferation, invasion, and metastasis." (PMID 31189966, 2019). "Gene set enrichment analysis (GSEA) functional classification of positive correlated mRNAs showed enrichment for genes belonging to various cancer-related pathways, such as the axon guidance involved in metastatization processes, metabolism of insulin, PI3K/Akt, and Ras signaling pathways." (PMID 31514456, 2019). "This phosphatase is a well-known regulator of the insulin signaling pathway; however, in the context of cancer its role is controversial, since it reportedly can either promote or prevent the development of cancer." (PMID 31484460, 2019). "While the insulin signaling pathway has been classically associated with metabolic types of action, evidence accumulated over the past several years identified the INSR as an important player in cancer development." (PMID 31771180, 2019). "We will then end by discussing how we should move beyond these disappointments with some thoughts on the potential of where research into the insulin/IGF-system may impact on future strategies to combat cancer." (PMID 30809194, 2019). "Furthermore, insulin can activate the expression of lipid biosynthesis genes in cancer cells through stimulating AKT downstream effector, mammalian target of rapamycin complex 1 (mTORC1)." (PMID 31315616, 2019). "First, insulin is known to prompt cancer cells to divide, so the slower rate of tumor growth could just be a side effect of metformin reducing the amount of insulin in the blood." (PMID 30765814, 2019). "Several experimental studies reported the ‘direct’ anti-cancer effects of metformin, which are distinct from its ‘indirect’ anti-cancer effects that are related to its anti-hyperglycemic actions, inhibition of hepatic gluconeogenesis, and reduction of insulin signaling." (PMID 31835318, 2019). "As a functional role for insulin/INSR in cancer has been suggested and markers of the tumour endothelium may be attractive therapeutic targets, we investigated the role of INSR in angiogenesis." (PMID 30559346, 2019). "Antidiabetic medications such as, insulin, sulfonylureas, dipeptyl peptidase (DPP) 4 inhibitors and glucose-dependent insulinotropic peptide (GLP-1) analogues increased the additional risk of different cancers to diabetic patients." (PMID 31831021, 2019). "Metabolic regulators such as insulin and the IGFs promote the required resetting of cancer cell metabolism and the initial clonal expansion; but then also help sustain the de-differentiation and acquisition of clonal heterogeneity that then favors progression and metastasis." (PMID 30809194, 2019). "IR, AMPK pathway, insulin pathway, and pathway in cancer are the key pathways." (PMID 31583009, 2019). "Insulin has been long assumed as a biological connection between metabolic disorders and cancers." (PMID 31315616, 2019). "The insulin signaling pathway has many effectors that can promote cancer development." (PMID 31315653, 2019). "The Danish Cancer Registry showed a higher mortality among patients treated with insulin." (PMID 30791870, 2019). "Moreover, in insulin-resistant patients, the IR-A overexpressed in cancer cells is likely chronically activated by high circulating insulin levels." (PMID 31480557, 2019). "In addition, KEGG pathway analysis revealed that the DE-ATGs were mainly enriched in pathways in cancer, insulin signaling pathway and proteoglycans in cancer." (PMID 31844032, 2019). "Moreover, obesity and high levels of insulin and IGF-1, as well as having diabetes mellitus are associated with worse survival in cancer." (PMID 31113478, 2019).
cancer (continued). "The action of insulin sensitizers on cancer is complex since they do not only affect low grade systemic inflammation and cell metabolism that impacts the disease but also directly affect cancer cell homeostasis and survival." (PMID 31244863, 2019). "This study identifies for the first time, a mechanism for insulin-driven cancer cell motility and supports the concept that targeting insulin signaling at the level of the PCa tumor may extend the therapeutic efficacy of ADT." (PMID 31379747, 2019). "Finally, the last important hub-bottleneck of the network is INS, insulin, which is known as cancer metabolism promoter." (PMID 32099604, 2019). "Dysregulation of metabolism and cancer-related pathways (metabolic pathways, pathways in cancer, calcium signaling, insulin signaling, cell adhesion, axon guidance, etc) could possibly function in promoting malignant transformation of HFHC-livers." (PMID 30367044, 2018). "Insulin resistant and the progression of cancer is closely related." (PMID 29793481, 2018). "Elevated circulating insulin level potentially favors the growth and aggressiveness of cancers." (PMID 30154386, 2018). "Metformin may have anti-cancer effects through direct (insulin-independent) and indirect (insulin-dependent) mechanisms." (PMID 29383018, 2018). "Numerous efforts have been made to block Insulin/IGF signaling pathway in cancer therapy." (PMID 29475434, 2018). "The two isoforms are expressed differently, IR-A is predominantly expressed in embryo and fetal tissues, central nervous system (CNS), hematopoietic cells and cancer cells, whereas IR-B is mainly expressed in the major insulin target tissues, i.e., liver, fat and muscle." (PMID 30453495, 2018). "A retrospective cohort study including nearly 63,000 diabetic patients admitted to general practices in the UK, found that MTF as single agent reduced cancer risk, especially for colorectal and pancreatic cancer when compared to sulfonylurea, MTF plus sulfonylurea, or insulin-based treatment." (PMID 30241339, 2018). "Overall, 48 patients (52%) were using insulin within 1 year after cancer diagnosis." (PMID 29682326, 2018). "The current study found insulin resistant and the progression of cancer is closely related." (PMID 29793481, 2018). "Focal adhesion kinase (FAK) is implicated in insulin signalling and cancer progression in various non-muscle cell types and plays a regulatory role during skeletal muscle differentiation." (PMID 29022062, 2018). "In addition to cancer related pathways, flavonoids were enriched in metabolic, steroid hormone biosynthesis, replication and repair, adherence junction, insulin signaling and several diseases related pathways." (PMID 30158870, 2018). "In contrast, a recent meta-analysis reported mixed results concerning insulin secretagogues and the risk of cancer, demonstrating a correlation between the administration of sulfonylureas and an increased risk of some cancers but not others 66,67." (PMID 30208162, 2018). "GR24 possesses anti-cancer and anti-apoptotic properties, enhances insulin sensitivity and mitochondrial biogenesis in skeletal myotubes, inhibits adipogenesis, decreases inflammation in adipocytes and macrophages and downregulates the expression of hepatic gluconeogenic enzymes." (PMID 30728949, 2018). "Although the first results of the clinical trials with compounds that target insulin/IGF signaling in PDAC have been disappointing, researchers have recently directed their research towards understanding the role of Insulin/IGF-1R signaling in the cross-talk between cancer cells and stroma." (PMID 29475434, 2018). "Serum analysis of mice that developed cancer showed, in parallel with the others, increased insulin (z = +5.06, p < 1 × 10−4) and C-peptide levels (z = +4.42, p < 1 × 10−4) and decreased glucose and leptin levels (z = −2.89, p = 0.004 and z = −2.99, p = 0.003, respectively)." (PMID 29662006, 2018).
cancer (continued). "Moreover, a retrospective study by Ma and colleagues analyzed the relationship between cancer-specific survival and C-peptide level, which directly represents insulin level, in PCa patients." (PMID 30097640, 2018). "For some type of cancers, insulin and oral hypoglycaemic agents (OHAs) may also represent risk or protective factors, although evidence is inconclusive." (PMID 29070034, 2017). "Hyperglycemic conditions also increase proliferation rate of several cancer cells, and this effect may be amplified when in combination with high insulin or IGF1 levels." (PMID 28880250, 2017). "Less potent insulin secretagogues, such as glinides do not appear to be associated with cancer risk." (PMID 29184536, 2017). "Its traditional anti-cancer mechanisms involve both indirect and direct insulin-dependent pathways." (PMID 27902459, 2017). "The contribution of Tribbles isoforms in mammals to insulin regulation and cancer is complex: recently, TRIB2 has been shown to be an Akt agonist, and an R107L mutation in TRIB1 that aligns with R141Q in TRIB3 promotes leukemogenesis by enhancing ERK phosphorylation and C/EBPα degradation." (PMID 29025897, 2017). "The crux of the debate has been whether insulin or analogs are associated to an increased risk of CRC (and cancer in general) and whether metformin is associated with a decreased risk of CRC." (PMID 28060743, 2017). "Insulin is a growth factor which can promote proliferation of cancer cells." (PMID 28930846, 2017). "We assessed their cytotoxic effect after sensitizing cancer cells with insulin." (PMID 29371977, 2017). "Metformin is by far the insulin sensitizer most studied in cancer prevention and therapy." (PMID 29184536, 2017). "In the cohort study of 327,112 new insulin users from five European countries, we addressed the relationship between insulin use and cancer incidence of ten site-specific cancers and any cancer, when mitigating methodological shortcomings and biases involved in previous studies." (PMID 28573394, 2017). "Elevated ImpL2 release can reduce systemic insulin signalling in flies with malignant tumors." (PMID 29615570, 2017). "Metformin is under intense investigation as an anti-cancer therapy for both tumor cell-autonomous activity as well as indirect activities in lowering systemic glucose and insulin that have largely been attributed to the reduced incidence of certain cancers in diabetic patients taking metformin." (PMID 28644886, 2017). "Accordingly, the IGF-1 receptor has a high expression in some cancer cells, which might in turn receive long-term proliferation signals that are activated by elevated insulin levels." (PMID 28977962, 2017). "The insulin/IGF system exhibits a key role in the process of cancer development and progression." (PMID 28880250, 2017). "Thus, since a high GL diet is more likely than a high GI diet to produce chronically elevated blood glucose and insulin, cancer should depend more on dietary GL than dietary GI36." (PMID 28851931, 2017). "A growing body of evidence showed that a downstream of AMPK, acetyl-CoA carboxylase (ACC), a precursor of lipogenesis, not only participated in metformin-induced improvements in insulin action in mice, but also modulated metformin-suppressed the proliferation rate of cancer cells." (PMID 28465536, 2017). "Insulin may promote cell proliferation, exerting a pro-survival effect on cancer cells, and may increase inflammation and oxidative stress." (PMID 28417914, 2017). "Whether these approaches may have specific benefits in insulin resistant patients with cancer is unknown." (PMID 29184536, 2017). "The use of insulin for cancer-specific treatment has been tested in several studies." (PMID 29371977, 2017).
cancer (continued). "Paradoxically, therapies that reduce GH action may ultimately prove to be healthier, in part because GH also possesses potent anti-insulin activities along with concerns that GH may promote the growth of certain cancers." (PMID 28933734, 2017). "By altering the endocrine-metabolic milieu of the host that is, reducing systemic levels of glucose and insulin), metformin may decrease cancer cell proliferation (reviewed in Pavlova and Thompson4)." (PMID 27775072, 2017). "For each of ten cancer sites studied, we estimated the rate ratios (RRs) by duration (≤0.5, 0.5–1, 1–2, 2–3, 3–4, 4–5, 5–6 and >6 years) of cumulative exposure to insulin glargine or insulin detemir relative to that of human insulin." (PMID 28573394, 2017). "In our study, carriers of the INS rs689 T allele had increased CRC risk in non-obese and E nonusers, with 35% and 80%, respectively, of the SNP–cancer association mediated by insulin/HOMA-IR levels." (PMID 29023587, 2017). "Studies by re-expression of klotho in cancer cells revealed that sKl acts as a tumor suppressor by inhibiting multiple signaling pathways that include the insulin/IGF-1 pathway, FGF pathway, Wnt signaling pathway, and transforming growth factor-β1 (TGF-β1) pathway." (PMID 29250031, 2017). "A relationship between increased levels of circulating insulin and cancer has been investigated, and the results indicated that cancer growth may be affected by IGF-1 signaling axis." (PMID 27903961, 2017). "Overall, all these functional interactions between insulin/IGFs and estrogens may concur to cancer growth and progression." (PMID 28275367, 2017). "It is known that increased insulin levels in the body can activate IGF-1 signaling which might furthermore promote the cancer cell proliferation." (PMID 28977962, 2017). "In one hand, the indoleamine is able to restore insulin-induced glucose uptake in skeletal muscle cells or increase the uptake in 3T3-L1 adipocytes while on the other hand, it reduces glucose uptake in cancer cells." (PMID 28933733, 2017). "Thus, insulin-stimulated Glut1 translocation is downstream of Akt S474 phosphorylation in this cancer cell line." (PMID 28589878, 2017). "We herein propose an integrated mechanism in cancer by which glycans alterations regulate the intricated signaling pathways mediated by the insulin/IGF system with impacts on cancer cell behaviour, cancer cell metabolism, cancer drug resistance and cancer stemness." (PMID 28880250, 2017). "First of all IGF-1 and insulin share overlapping downstream pathways of cancer cell metabolism." (PMID 27405474, 2016). "Finally, we examined the effect of metformin on insulin‐induced proliferation in Ishikawa cells, as insulin was reported to be mitogenic and anti‐apoptotic in various in vitro cancer models, including EC cell lines." (PMID 27636742, 2016). "IGF-1/insulin pathways were show as significant in cancer research." (PMID 27405474, 2016). "Insulin is a well-known growth factor with particularly strong mitogenic effects over cancer cells." (PMID 25916213, 2016). "On the other hand, performance of any degree of leisure-domain PA, even under the recommended threshold, has been described to reduce global, cardiovascular, and cancer-related mortality, accompanied by a favorable impact on insulin sensitivity and glucose tolerance." (PMID 27579182, 2016). "Data from RCTs do not support that insulin increases the risk of total cancer, although interpretation of the results is limited because cancer is not among the end points of interest." (PMID 25916213, 2016). "These approaches may be useful options in the ambition to exploit the full repertoire of insulin/IGF-1 modulation against cancer." (PMID 26878387, 2016). "In high-grade pre-malignant cervical lesions infected with HPV16 the IGFBP2 levels are reduced, suggesting that changes in insulin signaling may play a key role cancer progression." (PMID 27537218, 2016).